RIPK3 (receptor interacting serine/threonine kinase 3)
Diseases named in the same sentence as RIPK3 in open-access papers (continued):
Sharing a sentence is not in itself a finding about the gene and the disease.
tumor (continued). "Another aspect of PANoptosis that can exert anti-tumor immunity is embodied in RIPK3 and RIPK1, which are both essential components for the activation of necroptosis, and a core part of the interactions between the various PANoptosis signaling pathways." (PMID 38553639, 2024). "The tumor growth of the parental CT2A cells was inhibited upon activation of the RIPK3 suicide system compared with the controls." (PMID 39560995, 2024). "Another potential explanation is that the elevated baseline levels of reactive oxygen species (ROS) in tumor cells may render these cells more susceptible to ROS-inducing agents like thimerosal, leading to the activation of downstream signaling pathways, including RIPK3." (PMID 39349845, 2024). "This small molecule‐induced Z‐DNA turnover activated ZBP1, culminating in RIPK3‐mediated necroptosis and immune system engagement against the tumour." (PMID 38594879, 2024). "Using the RIPK3 CpG probes of its CpG island, low expression correlated with high RIPK3 methylation, supporting the idea of an epigenetically inactivated tumor suppressor." (PMID 38397165, 2024). "RIPK3, a key factor that regulates programmed cell necrosis, plays a crucial regulatory role in both inflammation and tumor development." (PMID 38461272, 2024). "Of note, among the drugs that induced tumor cell death or growth inhibition in our previous study, only thimerosal induced the RIPK3 dimerization reporter activation." (PMID 39349845, 2024). "The RIPK3 signaling pathway is associated with the pathogenesis of various cancers and exhibits both tumor-promoting and -suppressive activities, indicating that RIPK3 plays diverse roles in tumor development, metastasis, and recurrence." (PMID 38684668, 2024). "The expression of RIPK3 has been reported to be negatively correlated with tumor staging and is an effective prognostic indicator for various cancers." (PMID 38461272, 2024). "The upregulation of RIPK3 has been shown to increase the production of immunostimulatory cytokines in the tumor microenvironment, leading to a robust cytotoxic anti-tumor immune response." (PMID 38164277, 2024). "To assess the effect of the RIPK3 system on the tumor immune microenvironment (TIME), we analyzed the immune profile after activation of the safety switch in vivo." (PMID 39560995, 2024). "Metadata already showed an increased occurrence of methylation of RIPK3 in various tumor tissues and cancer cell lines, particularly within its CpG island." (PMID 38397165, 2024). "After a series of phosphorylation cascades, RIPK3-mediated necroptosis can inhibit tumor development through anti-tumor immunity." (PMID 38684668, 2024). "Shikonin is the first drug found to act in the RIPK1/RIPK3‐dependent necroptosis pathway and promotes tumour necroptosis." (PMID 38652105, 2024). "Previous studies have demonstrated that RIPK3-induced necroptosis promotes dendritic cell (DC) cross-priming of tumor-specific CD8+ T cells to repress tumor growth." (PMID 38858387, 2024). "To assess the synergistic therapeutic effect of the RIPK3 system and cancer cell–based therapy using live tumor cells, we sought to integrate this kill switch into the therapeutic tumor cells to treat established GBM tumors." (PMID 39560995, 2024). "Cell death induced by the RIPK3 safety switch inhibits tumor growth of parental CT2A cells and improves survival outcomes by reinvigorating the tumor immune microenvironment in vivo." (PMID 39560995, 2024). "Given that RIPK3 plays an important role in organ growth and tumor cell proliferation, it is considered a promising therapeutic target for various serious diseases." (PMID 38684668, 2024). "When decitabine is used to sustain RIPK3 (a vital factor in inflammation and necroptosis) hypomethylation or FAO targeting in RIPK3-KO mice, the anti-tumor immunity of TAMs is elevated and M2 polarization is attenuated, resulting in FA metabolism suppression." (PMID 38891772, 2024).
tumor (continued). "The significant increase in the methylation rate with increasing tumor stage suggests an epigenetic regulation of RIPK3 in advanced tumors." (PMID 38397165, 2024). "In mouse models, treatment with the RIPK1 inhibitor necrostatin-1 or the endothelial cell-specific deletion of RIPK3 reduced tumor cell-induced endothelial necroptosis, tumor cell extravasation, and metastasis." (PMID 38994937, 2024). "To investigate the tumor suppressive effect of RIPK3 after induction by epigenetic editing, we used VP160-dCas9 and TET1-dCas9." (PMID 38397165, 2024). "In several tumor cells, RIPK3 is often silenced by methylation near the transcriptional initiation site, which inhibits the activation of MLKL and fails to mediate necroptosis, consequently promoting tumor development." (PMID 38684668, 2024). "RIPK3-mediated necroptosis has been shown to promote tumor growth, development, and metastasis in some cancer models." (PMID 38684668, 2024). "Considering the importance of tumor-draining lymph nodes (TDLNs) for antitumor immune responses, we assessed the effect of RIPK3 safety switch activation on the TDLN." (PMID 39560995, 2024). "Further investigation is warranted to understand the mechanisms through which these kinase inhibitors activate RIPK3 expression in tumor cells." (PMID 38684668, 2024). "On the contrary, specific treatment with RIPK3-deficient endothelial cells attenuates the death of endothelial cells, suggesting that RIPK3-mediated necroptosis can promote tumor metastasis." (PMID 38684668, 2024). "Shikonin (SHI), a natural compound extracted from a Chinese herb, can mediate necroptosis to inhibit tumor growth by promoting RIPK3 phosphorylation, which subsequently promotes MLKL phosphorylation." (PMID 38684668, 2024). "Studies indicate that directing interventions towards ZBP1, caspases, NLRP3, RIPK1, and RIPK3 can trigger a robust anti-tumor immune response, facilitating the efficient eradication of cancer cells." (PMID 38553639, 2024). "On the other hand, cisplatin can trigger RIPK3-mediated necroptosis in tumor cells, leading to the release of cytosolic mtDNA, initiation of the cGAS–STING pathway, and secretion of IFN-I, consequently promoting the cross-activation of T cells through APCs." (PMID 38684668, 2024). "Compared with other existing safety switches, incorporating the RIPK3 system inhibited tumor growth, improved survival outcomes in tumor-bearing mice, and fostered long-term antitumor immunity." (PMID 39560995, 2024). "On the other hand, RIPK3-mediated necroptosis creates an immunosuppressive tumor environment that promotes tumor growth, development, and metastasis." (PMID 38684668, 2024). "When the expression of RIPK3 is low, tumor cells exhibit resistance to necroptosis, resulting in tumor growth." (PMID 38684668, 2024). "A new study shows that the expression of RIPK3 has a significant positive correlation with populations of tumor immune cells in various tumor types." (PMID 38553639, 2024). "In further steps, we used epigenetic editing to restore endogenous RIPK3 expression and its tumor suppressive effect." (PMID 38397165, 2024). "As a result, the expression of RIPK3 in such macrophages was augmented which effectively reversed the immunosuppressive activities of TAMs within the HCC tumor microenvironment." (PMID 38576612, 2024). "In xenograft models, RIPK3 has been shown to not only reduce tumor growth but also increase the sensitivity of tumor cells to chemotherapy." (PMID 38684668, 2024). "The tumor suppressive function of RIPK3 was evident by phenotypic determination using fluorescence microscopy, flow cytometry and wound healing assay." (PMID 38397165, 2024). "The rationale behind introducing the tumor cells expressing IFN-β in our study was to specifically assess the synergistic therapeutic effect when combined with the RIPK3 safety switch." (PMID 39560995, 2024).
tumor (continued). "For this purpose, we used the cell lines HEK and MeWo and compared the epigenetic editing results with tumor suppression of RIPK3 KD and RIPK3 wt by overexpression." (PMID 38397165, 2024). "It has also been shown that treatment of mice with the RIPK1-inhibitor necrostatin-1 (Nec-1s) or endothelial-cell-specific deletion of RIPK3 reduced tumor cell-induced endothelial necroptosis and tumor metastasis in mouse models." (PMID 38553639, 2024). "MLKL, a key executor of necroptosis, regulates tumor development, progression, and metastasis through both RIPK3-dependent and independent mechanisms, including receptor internalization, extracellular vesicle formation, and inflammation regulation." (PMID 39439891, 2024). "We report the creation and characterization of an optimized inducible RIPK3-driven necroptotic system that has a dual function of providing safety and inducing tumor eradication and long-term immunity in highly immunosuppressive tumors." (PMID 39560995, 2024). "Studies have discovered that RIPK3 expression was often silenced in cancer cells, and its defects were actively selected during tumor growth and development." (PMID 38553639, 2024). "Due to the natural turnover of RIPK3, proteasome inhibition is required to elicit cell death and to unleash full protective anti-tumor immune responses." (PMID 38858387, 2024). "In support of its anti-tumor role, lower RIPK3 expression correlates with worsened patient survival in lung cancer, chronic lymphocytic leukemia, colon cancer, malignant mesothelioma, and breast cancer." (PMID 38196632, 2023). "For example, due to the low content of RIPK3, necrosis cannot play an inhibitory role, so as to promote tumor growth." (PMID 37878133, 2023). "Also, similarly to what was observed for MLKL, we have previously shown that higher RIPK3 expression is associated with worse prognosis in diffuse glioma patients, suggesting that increased sensitivity to necroptosis may be also relevant to tumor progression." (PMID 37651429, 2023). "We performed PCR validation of NRGs and found that all genes except RIPK3 were significantly different between tumor and normal tissues." (PMID 37351504, 2023). "RIPK3 expression is downregulated in many tumor types, suggesting that RIPK3 has important functions in tumor suppression." (PMID 38196632, 2023). "In some tumor cell lines, two-thirds of the RIPK3 protein levels were decreased, indicating that tumor cells tend to escape necroptosis for survival." (PMID 37351504, 2023). "Targeting RIPK3, CD36, RIPK3 can directly regulate TAMs polarization toward an anti-tumor M1 phenotype." (PMID 37545527, 2023). "Most human tumor cell lines have a defect in RIPK3 expression and consequently fail to induce necroptosis as measured by MLKL phosphorylation." (PMID 36768641, 2023). "MLKL, along with RIPK1 and RIPK3, induce neutrophil extracellular traps, allowing them to act as a physical barrier to protect tumor cells from T or NK cell-mediated cytotoxicity." (PMID 37864090, 2023). "It is well established that necrotic cell death is a potent inducer of T cell responses and RIPK3-dependent necroptosis is especially effective for eliciting anti-tumor immunity [reviewed in]." (PMID 37287466, 2023). "We analyzed the association between the CNVs of necroptosis key genes, RIPK3 and MLKL, and the level of immune infiltration of various immune cells using the Tumor Immune Estimation Resource (TIMER) database." (PMID 37000317, 2023). "In an intestinal tumor model, RIPK3 in intermediate MDSC subpopulation was found to increase tumor size." (PMID 38149248, 2023). "The difficulty in separating these diverse signaling events has led to conflicting reports on the role of RIPK3 signaling in anti-tumor immunity." (PMID 38196632, 2023). "Previous studies have demonstrated that RIPK3-induced necroptosis promotes dendritic cell (DC) cross-priming of tumor-specific CD8+ T cells to achieve control of tumor growth." (PMID 38196632, 2023).
tumor (continued). "Most tumor cells show resistance to necroptosis thanks to the low expression of RIPK3, and the tumor would flourish." (PMID 37169000, 2023). "To further verify the regulatory relationship between TRAF6 and the RIPK1-RIPK3-MLKL signaling axis, we performed a subcutaneous transplantation tumor model of high TRAF6 expressing cells through RIPK3−/− and MLKL−/− mice of C57BL/6 genetic background." (PMID 36604411, 2023). "2-Hydroxyglutarate (2-HG), a product of mutant isocitrate dehydrogenase 1 (IDH1), binds to DNA methyltransferase 1 (DNMT1) and induces the hypermethylation of the RIPK3 promoter, thereby rendering tumor cells more resistant to necroptosis." (PMID 36849530, 2023). "Here, we demonstrate that MLKL act as an independent prognostic biomarker in LGG similarly to RIPK3 and supports the rationale that increased tumor expression of necroptotic molecules is detrimental to these patients." (PMID 37651429, 2023). "RIPK1 inhibitor necrostatin-1 or endothelial-cell-specific RIPK3 deletion inhibited tumor cell-induced endothelial necroptosis, tumor cell extravasation, and metastasis in mice." (PMID 36186479, 2022). "RIPK3, a regulator of necroptosis in tumor cells, also serves as a novel predictive marker for cancer immunotherapy personalization." (PMID 36685937, 2022). "According to our data, RIPK3 expression negatively correlated with prognosis and positively correlated with various tumor-infiltrating lymphocytes." (PMID 35907206, 2022). "In previous studies about COAD and necroptosis, the tumor-suppressing effects of RIPK3 and RIPK1 have been studied in COAD." (PMID 36505813, 2022). "The IHC staining results revealed that shMYOSLID CT26 tumour samples exhibited a higher expression of RIPK3." (PMID 36139524, 2022). "Analysis of the methylation status of necroptosis-related regulators between tumor and normal samples from 14 TCGA cancer types showed that RIPK3 and TLR3 exhibited DNA hypermethylation in multiple tumors." (PMID 35748782, 2022). "For example, the activation of the receptor-interacting serine/threonine-protein kinase 1 (RIPK1)/RIPK3/mixed lineage kinase ligand (MLKL)/C-Jun N-terminal Kinase (JNK)/IL-8 pathway can block tumor-cell reaggregation in colorectal cancer after radiotherapy." (PMID 35740953, 2022). "To study the Mlkl-independent tumor-repressive mechanism of Ripk3 signaling, we compared gene expression profiles among LK and LSK cells isolated from WT and Ripk3−/− mice 1 month after the fourth in a series of IRs using RNA-sequencing (RNA-seq) assay." (PMID 35561683, 2022). "For this purpose, N‐ethyl‐N‐nitrosourea (ENU), a potent mutagen, was sequentially injected for three times to evaluate rapid tumor development between two groups (Ripk3+/+ versus Ripk3−/− mice group)." (PMID 36161785, 2022). "There is also evidence that NKT cells are involved in RIPK3-mediated immune responses against tumor cells, due to RIPK3 deletion impairs tumor activation by NKT cells." (PMID 35912224, 2022). "RIPK3 activation causes cancer cells to exhibit TRIM28 derepression and improves the anti-tumor microenvironment." (PMID 36267408, 2022). "RIPK3 enhances the increase of premalignant intestinal epithelial cells and relates to tumor-inducing colitis through JNK and CXCL1 signaling pathways." (PMID 35884370, 2022). "Unfortunately, several tumor cells evade necroptosis efficiently by inhibiting the expression of RIPK3 via epigenetic control mechanisms." (PMID 35898880, 2022). "Several studies have reported that injecting necroptotic tumor cells, or engineered cells to specifically overexpress RIPK3 into mouse tumor models leads to killer T cell recruitment to TIME and attack tumor cells." (PMID 36466844, 2022).
tumor (continued). "Defective necroptosis, due to RIPK3 depletion, increases anti-tumor immunity, as evidenced by an increase in tumor infiltrating CD8+ T cells as well as a reduction in myeloid-derived suppressor cells (MDSCs) and tumor-associated macrophages (TAMs)." (PMID 36077828, 2022). "Necroptosis can activate RIPK1 and RIPK3 in the tumor microenvironment (TME) to promote antitumor immunity." (PMID 35756487, 2022). "In the present study, we revealed a tumor suppressor role for RIPK3 in spontaneous intestinal tumorigenesis." (PMID 33996591, 2021). "Cell death mediated by receptor interacting protein kinase 3 (RIPK3) has a critical tumor-suppressive function during leukemogenesis mediated by the induction of cell death and the inflammation-driven myeloid differentiation of the AML stem/progenitors." (PMID 34079078, 2021). "CRC tumor samples showed significantly decreased expression of RIPK3 relative to normal intestinal tissue samples." (PMID 33996591, 2021). "In this study, ectopic activation of RIPK3 promoted tumor antigen loading by tumor APCs (antigen presenting cells) associated with enhanced CD8+ T cell-mediated anti-tumor responses, which synergized with α-PD-1 co-administration to promote tumor clearance." (PMID 34419074, 2021). "In both MVT-1 and MMTV-PyMT tumors, while RIPK3 levels are very low/undetectable in the early stages of tumor development, RIPK3 expression is dramatically upregulated when tumor reaches certain sizes." (PMID 33976222, 2021). "In the mouse model used in this study, based on a genetically inducible tissue specific Kras-dependent oncogenesis, intact RIPK1/RIPK3 signaling favored the recruitment of an immunosuppressive tumor microenvironment." (PMID 34490126, 2021). "Anti-IL-6R antibody therapy suppressed STAT3 activation and attenuated tumor burden in Apcmin/+Ripk3-/- mice." (PMID 33996591, 2021). "In contrast RIPK1, RIPK3, and MLKL are widely expressed in human pancreatic ductal adenocarcinoma associated with robust manifestation of chemokines resulting in tumor promotion." (PMID 33567618, 2021). "Since RIPK1 is not essential for necroptosis of tumor cells during tumor development, we searched for possible tumor necroptosis mediators upstream of RIPK3." (PMID 33976222, 2021). "In summary, these data reveal that RIPK3 exerts tumor-suppressive roles in intestinal tumorigenesis." (PMID 33996591, 2021). "As expected, decreased levels of pSTAT3 and target genes were observed in anti-IL-6R-treated Apcmin/+Ripk3-/- mice and correlated positively with decreased tumor numbers." (PMID 33996591, 2021). "Of note, the size of the tumor distribution in Apcmin/+Ripk3-/- mice tended to be larger than Apcmin/+ mice." (PMID 33996591, 2021). "Most type of tumors have low RIPK3 expression and thus can resist necroptosis, which is conducive to tumor progression." (PMID 34869390, 2021). "While both RIPK1 and ZBP1 are capable of recruiting RIPK3 to mediate necroptosis, our results indicate that there is little redundancy among these two proteins in mediating tumor necroptosis during tumor development." (PMID 33976222, 2021). "Ubiquitin‐specific protease 22 (USP22) controls necroptotic cell death by regulating RIPK3 phosphorylation and RIPK3 K518 ubiquitination in human tumor cell lines." (PMID 33369872, 2021). "The downregulation of RIPK3 (receptor-interacting protein kinase 3) in tumor-infiltrating MDSCs potentiated COX-2-mediated PGE2 production which further reduced RIPK3 and promoted the immunosuppressive activity of MDSCs." (PMID 34620838, 2021). "Based on the critical tumor-suppressive function of RIPK3 during leukemogenesis, we determined the role of its downstream effector MLKL in AML." (PMID 34079078, 2021). "While there is a modest decrease of RIPK1 mRNA level in tumors, the mRNA levels of ZBP1 and RIPK3 are significantly increased in isolated tumor cells." (PMID 33976222, 2021).